NPY (neuropeptide Y)
Diseases named in the same sentence as NPY in open-access papers (continued):
Sharing a sentence is not in itself a finding about the gene and the disease.
Anxiety (continued). "Various measures to disrupt normal NPY function all result in anxiety-like behaviors and increased alcohol consumption." (PMID 23584814, 2008). "Another signaling molecule that can modulate anxiety and alcohol abuse through its actions on the amygdala is called neuropeptide Y (NPY)." (PMID 23584814, 2008). "For this, we exposed NPY-cre mice expressing the excitatory DREADD (hM3Dq) or a control vector (mCherry) in peri-LCNPY neurons to FS to induce stress-associated increases in LCNE excitability and anxiety-like phenotypes (cf., fig." (PMID 40700482, 2025). "Since NPY-deficient mice exhibited heightened anxiety levels compared with wild-type controls, as reported in previous studies, it appears that SFC exacerbates anxiety in rodents with pre-existing heightened anxiety traits." (PMID 40490517, 2025). "However, it is also involved in stress and anxiety regulation, with low levels of NPY being noted in anxiety and depressive disorders." (PMID 40711610, 2025). "Physiological factors, such as overexpression of neuropeptide Y (which may reduce BP) and fatigue/lower BP from anxiety induced hyperactivation, have also been proposed and described in detail elsewhere." (PMID 40207899, 2025). "Neuronal regulation of both mood and appetite is possibly linked through the central melanocortin system involving pro-opiomelanocortins, agouti-related protein, neuropeptide Y, and melanocortin receptors which regulate both feeding and development of anxiety and depression." (PMID 40529393, 2025). "Notably, increasing local NPY availability by chemogenetic peri-LCNPY neuron stimulation results in anxiety relief in animals previously exposed to stress." (PMID 40700482, 2025). "It is possible that bTBI could induce downregulation of NPY in the CNS in some mouse strains, possibly contributing to anxiety- or PTSD-like symptoms, and warrants further investigation." (PMID 40178780, 2025). "We next investigated whether this NPY-mediated LC-targeted neuromodulatory signal plays a role in stress-evoked anxiety." (PMID 40700482, 2025). "This ability of NPY to modulate the stress response and to reduce both fear-related behaviors and anxiety-/depressive-like symptoms suggests that NPY may be a promising target for developing new therapies for SAD with comorbid depression." (PMID 40490517, 2025). "Thus, AgRP neurons drive input-specific synaptic plasticity, enabling a selective shift in hunger and anxiety signaling during starvation through NPY." (PMID 38937485, 2024). "Furthermore, mice have been noted to display reduced anxiety-like behavior in the elevated plus maze, potentially attributed to elevated neuropeptide Y levels in the amygdala, indicating a potential resistance to stress-induced anxiety." (PMID 39086393, 2024). "We speculate that this reduction in NPY may promote a heightened state of anxiety, as NPY is robustly anxiolytic." (PMID 38352404, 2024). "Therefore, the fact that GTN mice showed photophobia, allodynia, and anxiety-like behaviors prompted us to further investigate reductions of NPY in the MHb using a mouse migraine model." (PMID 37231359, 2023). "Neuropeptide Y (NPY) and brain-derived neurotrophic factor (BDNF) exert anxiolytic functions in the amygdala, and their downregulation has been observed in association with increased anxiety and alcohol consumption after adolescent alcohol exposure." (PMID 38389820, 2023). "After intermittent alcohol exposure during adolescence, the methylation levels of brain-derived neurotrophic factor (Bdnf) exon IV and neuropeptide Y (Npy) increased in the amygdala of adult rats, this was accompanied by high alcohol intake and anxiety-like behavior." (PMID 37373281, 2023). "Furthermore, a single dose of NPY microinfused into the dHip of stressed mice one hour after stress exposure reduced manifestations of anxiety and avoidance behavior." (PMID 37149657, 2023).
Anxiety (continued). "Finally, we initiatively identified the key role of MHb NPY in the alleviation of allodynia and anxiety-like behaviors through the Y1 receptor in the GTN-induced migraine model." (PMID 37231359, 2023). "This suggests that agmatine regulates anxiety in the CeA via the NPY system." (PMID 36829752, 2023). "Besides its function in homeostatic feeding, the NPY system also plays an important modulatory role in learning and memory, cognition, anxiety, and neuroplasticity." (PMID 37630771, 2023). "In addition to its role in AIE-induced adult anxiety, NPY is also involved in the anxiolytic effects of acute ethanol." (PMID 38389820, 2023). "Therefore, this study compared the effects of Ninjinyoeito, Hochuekkito, and Juzentaihoto on psychiatric symptoms using neuropeptide Y knockout (NPY-KO) zebrafish, a suitable animal model for anxiety and low sociability." (PMID 37324500, 2023). "However, treatment with BIBP3226 and ALLO decreased the anxiety-reducing effect of ALLO suggesting that the anxiolytic effect of ALLO is mediated by acting on the NPY system via the NPY1R in some areas of the brain." (PMID 36829752, 2023). "To determine whether NYT or HET resulted in more anxiolytic Kampo-hozai, we evaluated the anxiety-like behavior of NPY-KO zebrafish fed with a diet containing 0.3% NYT or HET." (PMID 37324500, 2023). "Previous work suggests that the ability of NPY to decrease alcohol consumption may be in part due to its ability to relieve alcohol withdrawal-induced anxiety (Thorsell and Mathé, 2017)." (PMID 35800635, 2022). "NPY has a wide range of functions and plays an important role in the food intake, sexual behavior, information processing, cognition, learning and memory, control of blood pressure, sympathetic excitability, regulation of stress and anxiety." (PMID 36339882, 2022). "We explored the effects of repeated restraint stress and intermittent alcohol exposure during adolescence on the mRNA expression of many genes related to the CRH and NPY systems in the amygdala because this brain region is involved in the regulation of anxiety-like behaviors." (PMID 35327395, 2022). "Indeed, NPY and Y1 receptor agonists have been shown to decrease anxiety-like behavior, fear-suppressed food reinforcement, contextual fear, and social avoidance in rodents." (PMID 35800635, 2022). "Of these three peptide ligands, NPY, a highly abundant peptide ligand in the brain, can activate all four subtypes of the NPY receptor and is involved in various physiological processes such as food intake, stress response, anxiety, and memory retention." (PMID 35165283, 2022). "Human and animal studies show that NPY reduces anxiety and stress and may play a role in stress resilience." (PMID 36525411, 2022). "A physiological explanation could be the overexpression of neuropeptide Y, which seems to reduce BP and was observed in both individuals with anxiety and with depression." (PMID 35407607, 2022). "In addition, SCFAs stimulate EECs to releases neuropeptide Y, peptide YY, and other gut hormones such as ghrelin, which attenuate anxiety- and depression-like behavior." (PMID 35456041, 2022). "For example, NPY induces an anxiety state through Y2R but alleviates anxiety by binding to Y1R." (PMID 33708805, 2021). "Moreover, it has been proven that the elevation of NPY reduces anxiety, fear learning, and locomotor activity." (PMID 33670342, 2021). "In the future, the development of drugs capable of modulating NPY expression and NPY receptors in the NAc may contribute to the treatment of alcoholism, drug addiction, eating disorders, anxiety, and depression." (PMID 34298907, 2021). "We also investigated whether the effects of NPY on the expression of social fear might be due to altered anxiety-like behavior." (PMID 33918123, 2021).
Anxiety (continued). "These brain regions were selected because the amygdala and the septo-hippocampal circuits have strong NPY-ergic innervation, and are important components of the neural circuitry controlling anxiety-related behaviors, fear-related behaviors, social behaviors and stress responses." (PMID 33918123, 2021). "However, it is important to note that anxiety-related effects of NPY are exerted in the brain, whereas we assessed both soluble DPPIV and NPY levels in plasma." (PMID 34267682, 2021). "This study identifies the DLS and the CeA as brain regions mediating the effects of NPY on the expression of social fear and suggests that partly distinct neural circuitries mediate the effects of NPY on the expression of social fear and on anxiety-like behavior." (PMID 33918123, 2021). "Overall, it appears that NPY can regulate anxiety in females, however, it may be dose or site-specific." (PMID 34566592, 2021). "However, to date, few studies examining the role of accumbal NPY in anxiety and stress compared these effects to those of other brain regions, such as the amygdala and hypothalamus." (PMID 34298907, 2021). "These partly different results might suggest that the neural circuitries mediating the effects of NPY on social behavior and on anxiety-like behavior are different to some extent." (PMID 33918123, 2021). "Anxiety and depression are associated with altered intrinsic functional connectivity of brain networks, but the effect of NPY on functional connectivity is not known." (PMID 34867217, 2021). "Thus, NPY expression in the BNST is inversely related to stress responses including anxiety and ethanol consumption." (PMID 34975380, 2021). "Importantly, promising results have been obtained from clinical trials suggesting that intranasal NPY can reduce anxiety in persons with PTSD." (PMID 34975380, 2021). "By reducing anxiety, NPY might enable the mice to approach the social stimuli faster and therefore lead to a faster extinction of social fear." (PMID 34576305, 2021). "Endothelial dysfunction induced by NPY may be reduced NO bioavailability, partly due to Y2R-induced anxiety." (PMID 33708805, 2021). "Furthermore, in recent years, researchers have emphasised the role of NPY in the regulation of anxiety, cognition, mood, and stress levels." (PMID 33670342, 2021). "We also investigated whether the reduced expression of social fear in NPY-treated SFC+ mice might be due to a reduced anxiety-like behavior." (PMID 33918123, 2021). "However, intracerebroventricular (ICV) administration of NPY and Y1 receptor agonists attenuated the anxiety and depression-like effects of CCK-4 ICV administration in mice." (PMID 34298907, 2021). "By decreasing anxiety-like behavior, NPY might enable SFC+ mice to approach the social stimuli faster and, thereby, to express less social fear." (PMID 33918123, 2021). "It is possible that in females NPY plays a role in anxiety; however it may work in concert with other unknown, sex-specific mechanisms." (PMID 32867327, 2020). "The global deletion of NPY in the NPY KO mice could have triggered compensatory mechanisms specific to females pertaining to the regulation of anxiety behavior." (PMID 32867327, 2020). "Studies have confirmed that NPY neurons are involved in the regulation of anxiety in mice." (PMID 33123166, 2020). "Moreover, direct injection or overexpression of NPY in the brain exerts anti-anxiety effects in rodents, and knockout of NPY exacerbates the anxiety phenotype in mice." (PMID 33123166, 2020). "Genes regulating NPY have been shown to interact with environmental factors such as stress to increase susceptibility to negative emotional symptoms associated with anxiety and depression." (PMID 33192369, 2020). "Activation of NPY signaling, for example, increases food intake and decreases stress and anxiety." (PMID 33307547, 2020). "The group found a dose-response effect of intranasal NPY on the Beck Anxiety Inventory." (PMID 32867327, 2020).
Anxiety (continued). "The upregulation of NPY in O. latipes is a sign of fear and anxiety." (PMID 32414023, 2020). "A growing body of evidence indicates that NPY in the CNS plays a role in the stress response, and stress-related neuropsychiatric disorders such as anxiety, depression, and substance use disorder." (PMID 33192369, 2020). "Additionally, NPY plays a crucial role in body temperature (BT) regulation, weight control, glucose metabolism, anti-anxiety, and anti-depression, which are closely related to the immune response." (PMID 33123166, 2020). "Before the test, the participants were asked to complete the Glasgow Edinburgh Throat Scale (GETS), visual analog scale (VAS), and the Hamilton Rating Scale Anxiety/Depression and were then asked to test and measure the heart rate variability and serum hormone levels of SP and NPY." (PMID 32528966, 2020). "In addition, NPY is thought to have multiple functions, including changing the storage of fat energy and reducing anxiety and stress." (PMID 32414023, 2020). "We demonstrated that NPY-KO zebrafish have an anxiety phenotype and a stress-vulnerability like NPY-KO mice, whereby orx and/or catecholamine signalling may be involved in the mechanism actions." (PMID 32246073, 2020). "Furthermore, the loss of neuropeptides, such as NPY, PDYN and PENK, has also been associated with enhanced susceptibility to anxiety-like and depressive-like behavior in mice." (PMID 31251738, 2019). "Motivational state competition following the activation of AgRP/NPY neurons could be instrumental for suppressing fear and anxiety in the presence of food, conceivably by those AgRP/NPY projections directly targeting BNST, CeM, and PVT148." (PMID 31271235, 2019). "Several lines of evidence suggest that those neuropeptides, which are increased by hunger (NPY and AgRP), also reduce fear and anxiety, while others released upon refeeding and in particular during states of satiety are predominantly anxiogenic (α‐MSH, CRH, and CCK)." (PMID 31271235, 2019). "NPY plays an important role in depression, anxiety, and other pathological disorders." (PMID 31915447, 2019). "Decrease in NPY and PV expression in the hippocampus may explain the possible mechanism of hyperandrogenization induced anxiety." (PMID 31281833, 2019). "Adolescent alcohol exposure also alters other anxiety-related neuropeptides such as α-MSH or NPY." (PMID 30837923, 2019). "In males, we have previously shown that NPY infusion alleviates anxiety as measured by the percent of open and CA entries and duration and anxiety index, however the track length (or distance traveled) remains unchanged as compared to animals infused with vehicle and lower than unstressed controls." (PMID 30804766, 2019). "Thus, it can be suggested that differences in anxiety-related behaviors between sP and sNP rats can be mediated or maintained, in part, by altered NPY expression in specific BNST subnuclei." (PMID 31114482, 2019). "Additionally, intracerebroventricular administration of NPY decreases anxiety-like behavior in the EPM, Vogel's drinking conflict test and other operant conflict tasks." (PMID 31281833, 2019). "Furthermore, the administration of NPY showed potential prophylactic and curative beneficial effects on developed anxiety and depression." (PMID 30863280, 2019). "Neuropeptide Y is one of the most abundant neuropeptides in the central nervous system and regulates the stress response and emotional behaviors and has been suggested to be involved in anxiety, depression and posttraumatic stress disorder (PTSD)." (PMID 29973870, 2018). "In addition, our data suggest that GABA released from NPY+ cells plays a different role in adolescent anxiety-like behavior than what was previously shown in adults." (PMID 30024942, 2018). "As a result, therapeutic strategies that increase GABA transmission specifically from NPY+ cells could potentially be beneficial in treating anxiety and compulsive-type behavior in adolescents." (PMID 30024942, 2018).
Anxiety (continued). "To test whether the enhanced anxiety could potentially result from reduced NPY release, we used an ELISA to measure plasma NPY levels, and used immunohistochemistry to measure NPY levels in hippocampus and prefrontal cortex." (PMID 30024942, 2018). "Furthermore, 1 week after SPS exposure, when animals have developed symptoms of PTSD, treatment with intranasal NPY reduces anxiety-like and depressive-like behavior." (PMID 30186127, 2018). "In view of the role of the anterior BNST in anxiety- and stress-related behaviors, these findings suggest a scenario where NPY-positive neurons are preferentially active and responsive to afferent inputs, thereby contributing to adaptation of the organism to stressful environmental encounters." (PMID 30455634, 2018). "However, our results do support a role for inhibition from NPY+ cells in regulating innate behaviors dependent on the prefrontal cortex, specifically anxiety, nest building, and social dominance." (PMID 30024942, 2018). "It remains to be seen if the reduction in GAD67 in NPY+ cells in NPYGAD1-TG mice as adults leads to enhanced NPY release, which could contribute to the unexpected decrease in anxiety behavior." (PMID 30024942, 2018). "It remains to be determined whether Y1R agonists are sufficient to also produce the reduction in SPS triggered symptoms of anxiety obtained with intranasal NPY." (PMID 28469551, 2017). "Additionally, localized overexpression of NPY within the amygdala led to decreased anxiety, as well as alcohol intake, in rats, further confirming a role for endogenous NPY in regulation of anxiety-related behavior." (PMID 28824541, 2017). "In healthy subjects, intravenous administration of yohimbine has been reported to induce anxiety as well as relapse to alcohol seeking and craving for alcohol, increased plasma NPY, highlighting the role of NPY in regulating anxiety; this effect was attenuated in PTSD." (PMID 28824541, 2017). "Neuropeptide Y (NPY) may exert potent anxiolytic effects through Y1 receptors but augments anxiety through Y2 receptors." (PMID 28000031, 2017). "Finally, the anxiolytic-like action of excess NPY has been confirmed in pharmacological rodent models testing exogenously administered NPY in a variety of anxiety paradigms." (PMID 28081177, 2017). "Taking into account that NPY modulates both anxiety and depression through the same receptor type—Y1R, it seems possible that changes in total hippocampal NPY content may influence various behavioral patterns." (PMID 28582442, 2017). "In addition, innate HDAC2 overexpression and decreased H3K9 acetylation in the central nucleus of alcohol-preferring rats correlated with low levels of BDNF, Arc, and NPY and was accompanied with high levels of anxiety-like and alcohol-drinking behaviors." (PMID 27766083, 2016). "We found that the NPY Y1 receptor mRNA level was up-regulated in STSC and EC mice after predator exposure, and this finding is consistent with previous pharmacological studies that demonstrate NPY Y1 receptor-mediated anxiety and fear reducing effects of NPY in a PTSD model." (PMID 26016844, 2015). "Interneurons also use neuropeptides, such as cholecystokinin (CCK) and neuropeptide Y (NPY), as co-transmitters that exert profound effects on fear, anxiety, learned helplessness behavior and stress response, and stress was found to affect their expression as well." (PMID 26793083, 2015). "Nicotine-mediated cholinergic stimulation also involves the activation of neuropeptide Y and cAMP, which represents calcium dependent mechanisms involved in cholinergic hippocampal-mediated anxiety, epinephrine-mediated anxiety, and cholinergic neuromuscular stimulation." (PMID 26317007, 2014). "Furthermore, movement and anxiety are affected due the effect of nicotine on reward brain regions and brain stress systems involving dopaminergic regulation, epinephrine, neuropeptide Y, and neuromuscular nicotinic stimulation." (PMID 26317007, 2014).